MYC (MYC proto-oncogene, bHLH transcription factor)
Diseases named in the same sentence as MYC in open-access papers (continued):
Sharing a sentence is not in itself a finding about the gene and the disease.
liver cancer (continued). "Therefore, our study focused on discerning the regulatory mechanism of miR22hg and MYC in HCC development by using a liver cancer model." (PMID 37117191, 2023). "Hence, we further investigated the gene expression profiles and enriched biological processes in the male hep-c-MYC/AR-FL liver cancer." (PMID 36746917, 2023). "AR-FL co-expression showed moderate increases in the expression of these pro-oncogenic genes and could contribute similarly to the exacerbation of the c-MYC-driven liver cancer development in males, but at a much-reduced level." (PMID 36746917, 2023). "Along with the evidence from this research, c-MYC could be requisite in maintaining tumor growth and burden, further supporting the notion of its inhibition as a therapeutic strategy in primary liver cancer." (PMID 37628798, 2023). "For instance, the degree of MYC activity was correlated with OS in brain and liver cancers." (PMID 36688815, 2023). "In addition, the number of p-p65-positive cells was also obviously increased in MYC-ON mouse liver cancer treated with DU101 or DU102." (PMID 39872623, 2023). "Considering that activated AKT may also contribute to increased c-MYC stability by suppressing GSK-3β activity, we hypothesized that c-MYC might contribute to the DEN-induced liver cancer phenotype observed in the Ppp2r5d HE and HO mice." (PMID 37627221, 2023). "Most importantly, proteomic analyses determined that CCDC9B loss impaired protein levels of its partner, the MYC-regulator Influenza Virus NS1A Binding Protein (IVNS1ABP), creating sensitivity to bromodomain inhibitors in liver cancer cells exhibiting NSUN7 epigenetic silencing." (PMID 37173708, 2023). "SRC-mediated co-activation of anti-tumor target genes inhibits MYC-induced liver cancer." (PMID 35991574, 2022). "Consistently, PRMT5 is a direct MYC target gene in the Eμ-myc lymphoma and liver cancer models." (PMID 35439169, 2022). "Previous network pharmacological studies had also found that AR and MYC could play a key role in the process of viral hepatitis, liver cirrhosis, and liver cancer and inhibit the expression of AR, JUN, and MYC, which reduce the occurrence of liver cancer." (PMID 35330838, 2022). "The results support the hypothesis that PMEPA1 may be a major TGFβ effector and serve as a target for c-MYC activated liver cancer treatment." (PMID 33608500, 2021). "The activation of c-MYC can promote the resistance of liver cancer cells to sorafenib." (PMID 34663798, 2021). "SRC-2-mediated coactivation of anti-tumorigenic target genes suppresses MYC-induced liver cancer." (PMID 33593309, 2021). "It was reported that MYC inactivation could induce sustained regression of invasive liver cancer in a MYC transgenic mouse model." (PMID 33259779, 2021). "Moreover, GLS inhibition with BPTES prolonged the survival of a MYC-overexpressing mouse model of liver cancer, with MYC-dependent GLS expression." (PMID 34588983, 2021). "In a MYC-inducible model of liver cancer, glycolysis could be visualized by hyperpolarized 13C magnetic resonance spectroscopy and its activity could be attributed to the MYC oncogene." (PMID 34637026, 2021). "For example, Keratin 23 was considered a PPAR‐α dependent, MYC‐amplified oncogene that might remove rate‐limiting constraints on hepatocyte proliferation and lead to liver cancer." (PMID 33931972, 2021). "The effect of PPARα activation is the opposite in the liver cancer, PPARα activation enhanced the expression of MYC, which in turn enhanced the expression of the Krt23, a downstream target gene of the PPARα, thereby promoted the proliferation of the liver cancer cells." (PMID 33132907, 2020).
liver cancer (continued). "Here, we evaluated the specific contribution of FASN in this process, namely we assessed whether FASN suppression affects the growth of c-MYC liver cancer cells in vitro." (PMID 33187130, 2020). "The expression of FAM83H was transcriptionally controlled by MYC in liver cancer cells." (PMID 32564009, 2020). "Finally, TTP has also been shown to regulate glycolytic levels in hepatic cancer cells by lowering the expression of MYC, an important regulator of glycolysis." (PMID 32932781, 2020). "Given that MYC amplification and CTNNB1 mutation are the driver alterations in liver cancer, we thus detected whether these two TFs influenced RUVBL2 expression." (PMID 31572066, 2019). "The MYC oncogene is dysregulated in approximately 30% of liver cancer." (PMID 30833661, 2019). "3- CAMKIIG may increase hepatic cancer stemness characteristics by inducing the expression of MYC in β-catenin dependent manner and stemness markers, Oct4 and SOX2, expression via induction of AKT phosphorylation." (PMID 30944375, 2019). "Besides, c-MYC is an indicator of poor prognosis in liver cancer, whereas disease-free survival in patients showing c-MYC overexpression is significantly shorter." (PMID 28422055, 2017). "To determine whether SRC-2 suppresses MYC-mediated liver cancer, we employed a mouse model of MYC-induced liver cancer previously utilized in a SB mutagenesis screen." (PMID 28273073, 2017). "Jang KY reported that the high expression of MYC could promote the pathogenesis of liver cancer and that MYC was considered an indicator of the prognosis of liver cancer." (PMID 26046465, 2015). "Therapeutic interventions, which would simultaneously target signaling pathways governing both DLC1 and MYC functions in hepatocarcinogenesis, could result in progress in the treatment of liver cancer." (PMID 22580498, 2012). "Therefore, to investigate the role of SIRT1 in liver cancer and its relationship to c-Myc, we utilized a mouse model of liver tumorigenesis under the genetic control of conditional oncogenic c-MYC." (PMID 23024800, 2012). "Importantly, the anti-tumor effects of ACBP/DBI neutralization are not solely due to its hepatoprotective properties, as they persist in mouse models of HCC driven by oncogenes (e.g., β-catenin and MYC) or orthotopic injection of syngeneic liver cancer cells into immunocompetent hosts." (PMID 41315195, 2025). "Moreover, no mutations in MYC or MET genes are reported in this liver cancer cell panel, except for a MYC missense mutation in HCC1.1 and MET amplification in MHCC97 cells." (PMID 36433941, 2022). "In addition, MYC is a well-established driver of liver cancer initiation and progression, so the identification of novel MYC-regulatory pathways in this cancer may have profound scientific and clinical impact." (PMID 34937878, 2022). "Additionally, as MYC drives mRNA translation of programmed death-ligand 1 (PD-L1) in KRAS-/MYC-driven liver cancer, which favors immune escape of the tumor, treatment of those mice with eFT508 or anti-PD-L1 therapy significantly prolonged the survival of the mice and reduced metastasis." (PMID 32455578, 2020). "In experimental models, liver cancer development is greatly accelerated by the combined overexpression of FGF19 and MYC, resulting in more aggressive tumor phenotypes." (PMID 41328353, 2026). "In this study, we show that BET inhibition induces MYC-independent and glutamate dehydrogenase 1 (GDH1)-dependent glutamine metabolic remodeling in liver cancer." (PMID 39872506, 2024). "Together, we uncover an important epigenetic-metabolic crosstalk whereby BET inhibition induces MYC-independent and GDH1-dependent glutamine metabolic remodeling that can be exploited for innovative combination therapy of liver cancer." (PMID 39872506, 2024).
liver cancer (continued). "To explore the likely mechanisms by which AR-V7 potentiates the c-MYC-driven hepatocarcinogenesis, we performed a gene expression profiling of liver cancer developed in hep-c-MYC and hep-c-MYC/AR-V7 mice at 20 dpi by RNA-seq transcriptome analyses." (PMID 36746917, 2023). "Many genes like AKT-1, NFK β-1, c-MYC, STAT-3, JUN B, TGF-β1 have been involved in regulating the proliferation process in human liver cancer cells." (PMID 37053209, 2023). "In liver cancer, RPL11-mediated MID1 interacting protein 1 depletion reduced cell viability and colony formation by inhibiting MYC gene expression." (PMID 36869281, 2023). "Thus, the identification of novel factors synergistically exacerbating the c-MYC pathway in hepatocarcinogenesis could provide significant insights into the mechanisms of tumor heterogeneity, thereby improving treatment options in liver cancer." (PMID 36746917, 2023). "MYC deregulation has been identified as a key oncogenic driver in up to 60% of HCC cases, the predominant form of liver cancer." (PMID 36684069, 2023). "In further database analysis of human cancers, a higher expression of MYC mRNA was observed in the INTS14 mRNA high-expressing prostate and liver cancers." (PMID 35887071, 2022). "The corresponding genes of middle-stage CNV events including MYC, CNBD1, HEY1, RUNX1T1, CDH17, high expression of HEY1 gene promotes self-renewal of tumor stem cells, especially in liver cancer." (PMID 34453042, 2021). "Here we show that a combination of oncogenes that is characteristic of liver cancer (CTNNB1, TERT, MYC) induces senescence in human fibroblasts and primary hepatocytes." (PMID 34302118, 2021). "For example, amplification of oncogenes (EFGR, ERBB2, and MYC) occurs via BFB in up to ~70% of diverse tumor types (including breast, colorectal, lung, and liver cancers)." (PMID 32687060, 2020). "TTP silencing, likely by preventing the downregulation of specific TTP targets, including MYC, IER3, and AKT1, has been reported to equally restrain apoptosis induced by a MAPK inhibitor (PHA-781089) in hepatic cancer cell lines." (PMID 32932781, 2020). "In supporting with this notion, we found that the c-MYC and FBXL6 mRNAs have a notable correlation in liver cancer samples (R = 0.27, P = 1.3e-0.7)." (PMID 32576198, 2020). "The c-MYC/HBx-expressing transgenic mice rapidly produce tumors compared with c-MYC-expressing transgenic mice, illustrating that the synergistic effect of HBx and c-MYC accelerates the development of liver cancer." (PMID 30717368, 2019). "In this study, we first established C3A-derived liver cancer stem cells by OSKM method [OCT4, SOX2, KLF4, and c-MYC], termed C3A-induced cancer stem cells (C3A-iCSCs) which acquired self-renewal and stemness abilities." (PMID 26540347, 2015). "In that respect, a combined therapeutic approach, targeting both MYC and DLC1 signaling networks, have realistic potential to improve the treatment of liver cancer." (PMID 22580498, 2012). "The mechanism of this synergistic effect remains unclear and requires further research to elucidate the potential of treating liver cancer through FGF19 and MYC." (PMID 41328353, 2026). "We have identified a distinct mechanism of GDH1 upregulation by BET inhibition in liver cancer cells, which is through the downregulation of miR-30a independent of MYC." (PMID 39872506, 2024). "The macroscopic analyses showed that AR-FL co-expression moderately exacerbated the c-MYC-driven liver cancer in male mice, but not in female mice." (PMID 36746917, 2023). "Since AR-V7 and c-MYC cooperatively promoted liver cancer regardless of the sexes, we identified the genes that were commonly altered in male and female mice." (PMID 36746917, 2023). "Of the four cancer types studied in vitro, we focused on liver cancer, which has frequent overexpression of MYC without genetic amplification." (PMID 34937878, 2022).
liver cancer (continued). "We next assessed whether the clinical co-existence of high MYC and MET levels in HCC patients is functionally relevant to drive liver cancer." (PMID 36433941, 2022). "Our systematic review of a large number of researched studies shows that MYC has a known effect on the prognosis of liver cancer, although the Human Protein Atlas indicates that MYC is not prognostic in liver cancer." (PMID 36303795, 2021). "Moreover, overexpression of ZCCHC13 in liver cancer cells promoted cell cycle progression by facilitating the G1-S transition, which was related to aberrant activation of the ATK/ERK/c-MYC/CDK pathway." (PMID 30940166, 2019). "We deduced that the HypoM of MYC and the HyperM of MAX may activate the pathogenesis of arsenic induced liver cancer." (PMID 26046465, 2015). "While neonates up to 3 days do not develop HCC even with high MYC expression, neonates at 6 days of age or older demonstrated liver cancer cells that effaced the entire liver." (PMID 18628958, 2008). "Additionally, even though MSI2 target genes, such as MYC, LIN28A, and MET, have been extensively studied, the upstream mechanism driving MSI2 overexpression in liver cancer development remains unclear." (PMID 36599932, 2023). "Additionally, MYC protein can bind to specific regions on the CTR1 promoter and regulate its transcription, thereby increasing the concentration of the copper element within liver cancer cells." (PMID 37427098, 2023). "The Human Protein Atlas indicates that MYC is not prognostic in liver cancer." (PMID 36303795, 2021). "In addition, from the PPI sub-network of the genes adjacent to the aberrant DNA methylation sites, we found that among the key genes with a gene node degree greater or equal to 10, MYC, EIF4E, CDK4 and TGFB1 could stimulate the pathogenesis of liver cancer." (PMID 26046465, 2015). "Importantly, none of the control mice (wild-type for MYC and wild-type or mutant for Rb, n = 12) died from liver cancer within this first year (data not shown)." (PMID 21573126, 2011). "Significantly, various known YAP/TEAD1 targeted genes, such as BIRC5, AREG, CCND1, CTGF, and MYC, were not activated through SRGN-mediated YAP signaling in liver cancer cell lines." (PMID 40384866, 2025). "A negative correlation between GNMT and MYC expression was also observed in human HCC specimen and TCGA liver cancer dataset." (PMID 30760754, 2019).
osteosarcoma (241 papers, 1997 to 2026). A usually aggressive malignant bone-forming mesenchymal neoplasm, predominantly affecting adolescents and young adults. "In osteosarcoma, elevated c-MYC expression has been linked to resistance to both doxorubicin and methotrexate." (PMID 41438985, 2025). "High expression of Myc has been described as a prognostic biomarker in a variety of human STS (e.g. leiomyosarcomas, osteosarcomas and liposarcomas) and a high frequency of MYC gene amplification is associated with radiation-induced sarcomas." (PMID 36508875, 2023). "A recent study also shown that MYC is negatively associated with multiple immune cells and immune function in osteosarcoma, which supports the results of our study." (PMID 37055822, 2023). "Alterations in c-MYC on chromosome 8q24.21 is an important emerging prognostic factor that is implicated in chromosomal instability in osteosarcoma." (PMID 37894411, 2023). "MYC controls tumor initiation and progression by regulating the expression of its target genes; thus, constructing a risk signature of osteosarcoma MYC target gene set will benefit the evaluation of both treatment and prognosis." (PMID 37342196, 2023). "c-MYC overexpression is associated with higher rates of metastases, and shorter metastasis-free survival time in osteosarcoma." (PMID 37894411, 2023). "One hallmark characteristic of osteosarcoma is the upregulation of MYC, which occurs in nearly 41% of cases and is linked to an elevated risk of metastasis and reduced survival rates in patients with this disease." (PMID 37118828, 2023). "Recurrent copy number changes were identified in regions containing canonical osteosarcoma-associated genes, such as MYC and RB1, as well as in more novel regions such as 13q34." (PMID 35887382, 2022). "MYC is a multifunctional oncogene that is highly expressed in various human tumors and its mutations were detectable in more than 10% of osteosarcoma patients." (PMID 36586072, 2022). "Apart from the amplification of specific oncogenes including FGFR1 and MYC that have been associated with poor clinical outcomes, there has been limited success in identifying potential prognostic biomarkers for osteosarcoma." (PMID 33969640, 2021). "In a more recent study, it was found that the loss of MYC can reduce autophagy and further restrain cellular proliferation in osteosarcoma cells." (PMID 33430343, 2021). "In our studies the human osteosarcoma line U2OS expressing a conditional MYC-ER allele was used to induce oncogenic levels of MYC." (PMID 30902071, 2019). "They found that increased expression of MYC is associated with the spread of osteosarcoma and a poor prognosis because the protein product of MYC activates many super-enhancers, regions of DNA that increase the expression of cancer-related genes." (PMID 29644114, 2018). "In our study, through IP-MS analysis, we provided potential evidence that the interaction of ERK1/2 and DGKZ was closely linked to MYC-dependent osteosarcoma development." (PMID 30662872, 2018). "In this study, we investigated the molecular mechanisms underlying MYC amplification and overexpression in regulation of osteosarcoma." (PMID 29644114, 2018). "Overall, these data revealed that MYC expression is associated with progression and poor prognosis of osteosarcoma." (PMID 29644114, 2018). "Second, the c-MYC sequence-containing plasmid (pMEXr) increased the frequencies of mutations in human osteosarcoma U2OS cells, and transient DHX9 deficiency exacerbated these mutations, which comprised of deletions for the most part." (PMID 24049074, 2013). "MYC inhibition was suggested to cause differentiation of osteosarcoma cells into mature osteocytes in a mouse model." (PMID 21437228, 2011).